FAS (Fas cell surface death receptor)
Diseases named in the same sentence as FAS in open-access papers (continued):
Sharing a sentence is not in itself a finding about the gene and the disease.
colon carcinoma (41 papers, 2003 to 2025). "Many colon tumour-derived cell lines exhibit loss of sensitivity to FAS-mediated apoptosis in vitro." (PMID 17551494, 2007). "This investigation reveals a suppressive immune landscape in PIR‐high and FAS‐low expression human colon cancer." (PMID 38148593, 2024). "Consistently, Western blot analysis showed an increase expression of p‐NFκB2, NIK, and FAS in the colon tumors of PIR‐knockout mice as compared with wild‐type mice." (PMID 38148593, 2024). "A study on verticillin A, a selective inhibitor of SUV39H1, reported its effect on the increased FAS transcription and apoptosis of colon carcinoma cells." (PMID 36064736, 2022). "Human colon-tumor cell line LS411N is a high-grade primary colon-tumor cell line that also has lost FAS expression." (PMID 35053524, 2022). "Overexpression of codon usage-optimized FAS in metastatic mouse colon-tumor cells enabled FASL-induced elimination of FAS+ tumor cells in vitro, suppressed colon tumor growth, and increased the survival of tumor-bearing mice in vivo." (PMID 35053524, 2022). "We determined in this study that restoring FAS expression alone is sufficient to suppress established metastatic colon tumor xenograft growth in vivo." (PMID 35053524, 2022). "Literature indicates that FAS can be repressed by its promoter DNA hypermethylation in human colon tumor cell lines." (PMID 35053524, 2022). "Codon-usage optimization resulted in high levels of FAS protein on the metastatic colon tumor cell surface after ectopic expression." (PMID 35053524, 2022). "Our data determined that tumor-selective delivery of FAS DNA nanoparticles is sufficient for suppression of human colon tumor growth in vivo." (PMID 35053524, 2022). "FAS expression was down-regulated in all colon cancer tissues when compared to expression in normal colon tissues." (PMID 25605245, 2015). "Prevalent expression of DR4, 5 and FAS in both human colon cancers was confirmed by RT–PCR analysis." (PMID 17551494, 2007). "A recent study has also reinforced the notion that colon cancers are resistant to FAS-mediated apoptosis." (PMID 15494722, 2004). "We also found that AS1842856 treatment for 48 h induced the FAS gene in HCT116 colon cancer cells." (PMID 36602390, 2023). "An essential question then is whether restoring FAS expression alone is sufficient to suppress colon tumor growth." (PMID 35053524, 2022). "Verticillin A was found to be a new selective HMTase inhibitor that inhibits H3K9me3 to restore Fas expression, indicating that H3K9me3-mediated FAS transcription silencing is a dominant mechanism by which colon cancer cells evade host cancer immune surveillance." (PMID 31569621, 2019). "In addition, G9a regulated the expression of FAS to modulate the resistance of metastatic colon cancer cells to 5-fluorouracil in vitro and in vivo." (PMID 27531902, 2016). "To determine whether the expression levels of FAS in the colon cancer cell lines are comparable to the levels of MIR-196B, we carried out qRT-PCR or western blot analysis using the total RNAs or proteins isolated from SW480 and HT29 cells." (PMID 25605245, 2015). "SW620 cells have acquired genetic defects in apoptotic pathways and thus are resistant to FAS mediated apoptosis, which could be a potential mechanism of how some colon cancer cells escape the immune system." (PMID 26703577, 2015). "Moreover, liver metastases of murine colon carcinoma show an up-regulation of FAS-L on tumor cell surface with a decreased expression of FAS from day 10 on." (PMID 20205946, 2010).
colon carcinoma (continued). "So, FAS expression might be depend on endogenous MIR196B expression in colon cancer cell lines." (PMID 25605245, 2015). "Five genes (FAS, VWA5A, SPTBN2, PCK1, and TIMP1) significantly affect the prognosis of patients with colon cancer." (PMID 34957118, 2021). "In colon cancer cells, where the FAS receptor is strongly expressed, a study showed that PTPN13 silencing with siRNA improves their sensitivity to oxaliplatin by increasing FAS-induced apoptosis." (PMID 37895093, 2023). "Finally, the ARGPI was constructed based on five apoptosis genes (FAS, VWA5A, SPTBN2, PCK1, and TIMP1), which can effectively improve the prediction of colon cancer progression." (PMID 34957118, 2021). "Although this might suggest that during the transformation process, colon epithelial cells lose sensitivity to FAS-mediated apoptosis, it is unclear whether FASL upregulated in colon cancer leads to any increase in apoptosis of the tumour cells in vivo." (PMID 17551494, 2007). "Furthermore, FAS is negatively correlated with PIR, and positively correlated with NFκB2 and NIK in 54 paired colon cancer patient samples." (PMID 38148593, 2024). "Moreover, we analyzed a set of colon cancer cell lines from GEO database (GSE28567) and also found negative correlation of FAS with PIR and positive correlation with NFκB2 and NIK." (PMID 38148593, 2024).
glioma (38 papers, 2005 to 2026). A benign or malignant brain and spinal cord tumor that arises from glial cells (astrocytes, oligodendrocytes, ependymal cells). "The majority of the signaling pathways are related to cellular metabolisms, and others, including the WNT and FAS signaling pathways, have been linked to glioma pathogenesis." (PMID 36980325, 2023). "Copy number loss of the “death receptor” FAS was found in 35% (13/38) of gliomas, which could affect the gliomagenesis and response to therapy." (PMID 35748782, 2022). "Of the seven prognostic necroptosis genes, RIPK1, RIPK3, FAS, and FADD were used to construct the risk signature that accurately predicts the prognosis of glioma patients." (PMID 35719998, 2022). "Namely, Ptgs2 inhibits apoptosis in glioma xenografts, while Fap over-expression increases astrocytoma resistance to FAS-mediated apoptosis." (PMID 26517510, 2015). "The risk scores of glioma patients were calculated based on the coefficient and expression levels of each gene and the formula was as follows: risk score = 0.431 * RIPK1 +0.227 * RIPK3 + 0.302 * FAS +0.373 *FADD." (PMID 35719998, 2022). "Furthermore, amplification peaks of oncogenes (PIK3C2B, PDGFRA, EGFR, CDK4), and deletion peaks of tumor suppressor genes (TUSC1, CDKN2A, CDKN2B, PTEN, FAS, BNIP3) were detected in the gliomas with a high risk score." (PMID 32023222, 2020). "Furthermore, the total protein and surface levels of FAS-receptor notably increased after irradiation, potentially allowing the paracrine/autocrine mechanism of FAS-L/FAS-mediated apoptosis in glioma cells." (PMID 30783513, 2019). "Here, we investigated whether expression of the death receptor FAS was modulated by DAC on glioma cells." (PMID 27579489, 2016). "In addition, FAS signaling can result in other functions, including the maintenance of stem cell-like programs in glioma cells." (PMID 27579489, 2016). "Given that BA has previously been implicated in blocking diverse canonical YY1/FAS, ERβ, insulin/IGF‐1, MAPK/ERK and Notch signalling pathways in different pathological models, we next investigated which pathway was responsible for UBE2T downregulation in glioma." (PMID 41486508, 2026). "As shown by the bean plot, 7 genes (RIPK1, RIPK3, FAS, FADD, FASLG, TLR3, and TNF) were upregulated in the glioma tissues with p <0.001." (PMID 35719998, 2022). "In co-cultures of cytotoxic T cells with glioma cell lines (U251 and GL261), vorinostat and sodium butyrate also enhance FAS/FASL and Perforin/Granzyme B pathway-mediated glioma cell apoptosis." (PMID 32560120, 2020). "The high expression of TLR3 in lower grade glioma (LGG) and LUSC; FASLG in LGG, UVM, KIRC, and THYM; RIPK3 in LGG, KIRC, and LUSC; RIPK1 in LGG and THCA; FAS in LGG, UVM, and THYM; MLKL in LGG, UVM, and LUAD; FADD in LGG and HNSC; and TNF in UVM and CESC was associated with poor survival." (PMID 35748782, 2022). "It has been reported that CBX5 and H3K9me3 are enriched in the FAS and PUMA promoters in glioma, indicating that CBX5 could suppress apoptotic activators by sustaining the methylation level of H3K9me3." (PMID 36263018, 2022). "It is known that expression of the cell death receptor FAS is heterogeneous in glioma, and glioma cell lines may differ in sensitivity to FASL-mediated cell death due to low surface FAS expression or due to the expression of apoptosis-regulating genes." (PMID 27579489, 2016).
Autoimmunity (37 papers, 2006 to 2026). The occurrence of an immune reaction against the organism's own cells or tissues. "ALPS is a disorder characterised by autoimmunity and lymphoproliferations associated with mutations in genes involved in FAS-mediated apoptosis, with FAS itself as the most frequently affected gene." (PMID 40748381, 2025). "Most patients with ALPS due to a FAS mutation present at a young age (median age of onset 2, 7 years) with lymphadenopathy, splenomegaly, and autoimmunity, mainly but not limited to autoimmune cytopenia." (PMID 37702894, 2023). "We will also describe current knowledge about somatic mutations in FAS, together with their possible underestimation and a potential disease-contributing role in multifactorial autoimmune disorders." (PMID 35059842, 2022). "For example, autoimmune disorders and lymphomas in mice and humans that are linked to somatic and germline FAS mutations." (PMID 34440825, 2021). "Somatic FAS mutations in non-Hodgkin's lymphoma are often seen in patients with a prior history of autoimmunity." (PMID 31694869, 2019). "As LRBA regulates CTLA4 trafficking, its deficiency has been linked to autoimmunity and lymphoproliferation, which could help explain the clinical heterogeneity among carriers of the same FAS variant." (PMID 40755914, 2025). "Moreover, somatic FAS mutations identified in patients of non-Hodgkin’s lymphoma are mainly among cases with a prior history of autoimmunity." (PMID 34440825, 2021). "Indeed, patients or mice harboring an FAS deficiency develop an early-onset lymphoproliferative disease with autoimmunity (essentially against platelets and red cells)." (PMID 29686686, 2018). "However, sporadic autoimmunity might result from a FAS mutation in a single B cell or T cell clone, paired with other checkpoint deficits." (PMID 34440825, 2021). "The disruption of these genes has been associated with autoimmunity and lymphoid cancers, such as BIM deficiency and FAS mutations." (PMID 34440825, 2021). "Although FAS is a natural regulatory checkpoint of T cells, it plays a role in autoimmunity and cancer, and activation-induced cell death is involved in loss of CD4+ and CD8+ cells in HIV patients." (PMID 33361110, 2021). "This is an important regulatory mechanism against autoimmunity because mice and humans with defects in the FAS pathway develop systemic autoimmunity." (PMID 21573156, 2011). "Responsiveness to FAS-signaling contextually varies for pro-inflammatory and anti-inflammatory cells, and is reported to subsequently decide whether autoimmunity develops." (PMID 35511484, 2022). "Hence, ALPS and more common disorders may be significantly interconnected, and future research may shed more light on the role of FAS signaling in both autoimmunity and cancer." (PMID 35059842, 2022). "We provide evidence that a small subset of CD4+IL-6R+ TEM cells from carriers of the “non-risk/CC’ genotype show higher sensitivity to FAS agonist-induced expression of early apoptotic markers (Annexin V+ cells), potentially leading to decreased survival of pathogenic T cells in autoimmunity." (PMID 35911690, 2022). "Although the role of FAS-mediated apoptosis in immunity and elimination of autoreactive lymphocytes are clear, but the function of FAS or FASL as the markers of apoptosis in autoimmune disorders, especially SLE, needs more investigations." (PMID 24348139, 2013). "In this manner, non-apoptotic FAS signaling has been shown to prevent lymphoproliferation and autoimmunity, and promote proliferation and “precocious differentiation” of naïve T cells, with implications for adoptive T cell therapies." (PMID 38074985, 2023). "Studies in mice originally noted that double heterozygous subjects (i.e., lpr/+, gld/+) for murine analogs of FAS and FASL could develop lymphoproliferation and autoimmunity." (PMID 35059842, 2022).
Autoimmunity (continued). "However, these two key tolerance checkpoints are unable to compensate for each other, since (i) FAS-mediated apoptosis does not control the autoimmunity that develops in FOXP3-deficient patients and (ii) Tregs do not control the autoimmunity observed in FAS-deficient patients." (PMID 29686686, 2018).
COVID-19 (37 papers, 2020 to 2025). A disease caused by infection with severe acute respiratory syndrome coronavirus 2. "Our genetic evidence suggests that FAS is positively associated with the severity of COVID-19 and that CD40 is protective against severe COVID-19." (PMID 37397483, 2023). "Proteins that exhibited association only in one of the COVID-19 phenotypes included circulating FAS and THBS3." (PMID 34402426, 2021). "The quantification of gene expression revealed that individuals with severe COVID-19 had higher levels of FAS and FASL expression." (PMID 39859379, 2025). "In this study, we investigated the influence of polymorphisms in the FAS and FASL genes, FAS and FASL gene expression, and plasma cytokine levels on COVID-19 severity and long COVID occurrence." (PMID 39859379, 2025). "This is one of the first studies to evaluate the frequency of FAS and FASL polymorphisms with the severity of COVID-19." (PMID 39859379, 2025). "Lymphopenia and leukopenia have been observed in patients with COVID-19, which can be due to increased expression of FAS and FAS-L in T-cells, B-cells, and NK cells and as a result of increased apoptosis in these cells." (PMID 37396915, 2023). "The high expression of FAS on the surface of B cells highlights B cell senescence in active COVID-19 cases, further strengthening our finding of diminished MHC Class I mediated antigen presentation." (PMID 36532041, 2022). "Surprisingly, we also observed a higher expression of FAS in the B cell population (Naïve B cell, Class-switched Memory B cells), indicating an abnormal antigen presentation and antibody response in the COVID-19 patients." (PMID 36532041, 2022). "Our work provides a prioritised list of host targets potentially exploited by SARS-CoV-2 and is a precursor for further research on CD209 and FAS as therapeutically tractable targets for COVID-19." (PMID 34402426, 2021). "However, this study only evaluated two polymorphisms in the FAS gene and two polymorphisms in the FASL gene, but there are other polymorphisms in these genes that need to be evaluated in COVID-19." (PMID 39859379, 2025). "In this context, this study evaluated whether polymorphisms in the FAS and FASL genes may be associated with the severity of COVID-19 and the development of long-term COVID-19." (PMID 39859379, 2025). "Furthermore, six proteins partially mediated the causality of LTL on COVID-19 outcomes, including BNDF, QPCT, FAS, MPO, SFTPB, and APOF." (PMID 38882679, 2024). "Finally, six plasma proteins were found to mediate the causal effect between LTL and COVID-19 outcomes, such as BDNF, QPCT, FAS, MPO, SFTPB, and APOF." (PMID 38882679, 2024). "FAS (OR [95% CI] = 0.98 [0.97, 1.00], p = 4.56 ×10-2, proportion = 8.0%) and MPO (OR [95% CI] = 0.98 [0.97, 1.00], p = 2.13 ×10-2, proportion = 8.1%) partially mediated the causal effect between LTL and COVID-19 severity." (PMID 38882679, 2024). "In conclusion, this MR study provides genetic evidence supporting that increased expression of FAS may be associated with the risk of severe COVID-19, with a possible protective effect of CD40 against COVID-19." (PMID 37397483, 2023). "It has been demonstrated that the FAS pathway is deeply involved in the pathogenesis of severe COVID-19 rather than susceptibility to the infection, and that elevated plasma FAS levels increase the risk of detrimental outcomes." (PMID 36287942, 2022). "Moreover, there was increased expression of CD95 in samples from COVID-19 patients that correlated with disease severity, and FAS− cells were particularly depleted in all patients." (PMID 33361110, 2021). "Two proteins, called IL-6R and FAS, were involved in the immune response and could be responsible for the immune over-activation often seen in severe COVID-19." (PMID 34402426, 2021).